NFIX (nuclear factor I X)
Diseases named in the same sentence as NFIX in open-access papers (continued):
Sharing a sentence is not in itself a finding about the gene and the disease.
cancer (continued). "This is the case of RhoA/ROCK and JUNB signaling pathways that regulate NFIX expression during myogenesis and are involved in cancer cell proliferation and invasion." (PMID 36901722, 2023). "In this review, we explored the role of NFIX in cancer and its crosstalk with oxidative stress pathways." (PMID 36901722, 2023). "NFIB and NFIX have been shown to act as either oncogenes or tumour suppressors across various cancers." (PMID 36569748, 2022). "Transcriptional regulatory networks indicated HMGA1 as the top-ranked regulator of up-regulated TFs, which promotes epithelial-to-mesenchymal transition in cancer and associated with PAH; NFIX is the top-ranked regulator of down-regulated TFs." (PMID 36303246, 2022). "This motif corresponded to the binding site of nuclear factor 1 X-type (NFIX), a TF best known for its role in brain development but also implicated as tumor suppressor in various cancers." (PMID 34458153, 2021). "A third well-established cancer gene in our significant results was NFIX (Nuclear Factor I/X (CCAAT-binding transcription factor))." (PMID 27602958, 2016). "Furthermore, NFIX functions as a downstream target gene of microRNAs, impacting the development of malignant tumors." (PMID 40000619, 2025). "However, several studies have revealed that NFIX can also have a tumor suppressor role, demonstrating that NFIX has a complex and cancer-type dependent role." (PMID 37686043, 2023). "The results suggested that NFIX was downregulated in most cancers." (PMID 37686043, 2023). "Given the crucial function of NFIX in cell differentiation during embryonic development, it is possible that a potential link between NFIX, oxidative stress, and cancer cell dedifferentiation might be a pivotal factor in tumor progression." (PMID 36901722, 2023). "Altogether these studies suggest that NFIX may be a key player during cancer onset and progression, modulating several pathways implicated in tumorigenesis." (PMID 36901722, 2023). "However, some studies suggest that NFIX can also have a tumor suppressor role, indicating a complex and cancer-type dependent role of NFIX." (PMID 36901722, 2023). "A better understanding of how NFIX crosstalks with the oxidative stress response may provide yet another application for the modulation of NFIX levels in cancer treatment." (PMID 36901722, 2023). "In humans, NFIB and NFIX have been related to human development and cancer." (PMID 36569748, 2022). "NFIX is a member of a family of transcription factors that are involved in regulating the transcriptional activity of genes; and has been involved in cancer progression in a number of cancers including breast and esophageal." (PMID 27602958, 2016). "Previous studies suggest that NFIX may be a promising prognostic marker, and even though more research is needed to fully understand the relationship between NFIX and ROS in the context of cancer, it is possible that targeting NFIX offers a means of modulating ROS levels in cancer." (PMID 36901722, 2023). "In summary, NFIX might perform various functions in different cancers." (PMID 37686043, 2023). "In addition, these two studies have not explored the underlying mechanism of how NFIX modulates the migration of cancer cells." (PMID 32291386, 2020). "More interestingly, seven different genes (ECH1, PEX5, MLF2, NFIX, TSPAN9, SAMD4B, and NFKBIB) were associated with another drug C646, which is a small molecule inhibitor targeting histone acetyltransferase p300, an enzyme that alters the cancer transcriptome in the lung, colon and pancreas." (PMID 29207666, 2017). "RTKN2, NFIX, PTX3, BMP2 and LOXL2 of the ceRNA network play an important role in cancer progression." (PMID 34394080, 2021). "Hsa-miR-223-3p targets the EPB41L3, a potential tumor suppressor gene, the NFIX gene that regulates both cell proliferation and migration, the SLC2A4/GLUT4 is a glucose transporter and a biomarker for many types of malignant tumors." (PMID 31540229, 2019).
cancer (continued). "Both NFIX and NFIB play a key role in development and cancer." (PMID 37817005, 2024). "However, the exact mechanisms that contribute to the alterations of NFIX mRNA or protein expression in cancer have not yet been fully described." (PMID 36901722, 2023). "And based on qRT-PCR results, after overexpressing miR-744-5p, the expression level of UBE2L3 was inhibited in cancer cells but no significant changes were presented in LRP3 and NFIX expression." (PMID 33726770, 2021). "We also included the linear isoform of nuclear factor I X (NFIX) in this experiment as a control, since its interaction with YBX1 is not known and the functional variations of the circular and linear NFIX in cancer cells are not yet well studied." (PMID 38866007, 2024).
tumor (22 papers, 2008 to 2025). "Besides NFIX protein being associated with oxidative stress in different contexts, circNFIX has also been shown to have an impact on both tumor progression and oxidative stress." (PMID 36901722, 2023). "In this study, we discovered that the NFIX gene has a variety of connections with different driver genes, oncogenes, and tumor suppressors in LUAD and LUSC." (PMID 37686043, 2023). "The results of paired difference analyses in the TCGA database showed NFIX was downregulated in tumor tissues of LUAD and LUSC compared to adjacent normal tissues with p < 0.05." (PMID 37686043, 2023). "The results indicated that NFIX gene expression had a significantly different distribution in age, gender, and tumor stage in LUAD." (PMID 37686043, 2023). "The analysis of tumor suppressors showed that NFIX had a positive correlation with different tumor suppressors, among which TMPRSS2 had the highest correlation coefficient." (PMID 37686043, 2023). "The results from FFPE tumor sample sequencing reveal a novel fusion transcript involving Nuclear Factor I X (NFIX), mapping to 19p13.2 and STAT6, mapping to 12q13.3." (PMID 34299133, 2021). "To gain insight into the functional significance of NFIX in GBM, we orthotopically implanted NFIX deficient GBM cells into the hippocampus of nude mice and we demonstrate that NFIX exerts tumor-promoting role in malignant GBM development." (PMID 32291386, 2020). "NFIX deficiency impairs the migration of GBM cells and inhibits the tumor growth in the hippocampus of immunodeficient nude mice." (PMID 32291386, 2020). "Taken together, all the results collected from our study manifested that LINC00511 was a tumor promoter to sponge miR-625-5p by targeting NFIX in GC cell." (PMID 31889903, 2019). "Overexpression of NFIX in MCF7 cells significantly inhibited tumor growth in vivo." (PMID 40000619, 2025). "We also note the proapoptotic protein PMAIP1 (NOXA) that was downregulated in the drug-adapted tumors, and transcription factors NFIX, EGR1, and HES2 implicated in tumor promotion or suppression, which were differentially affected by LT everolimus and the drug combination." (PMID 39541354, 2024). "This can reveal when NFIX acts as an oncogene and when it acts as a tumor suppressor." (PMID 36901722, 2023). "While some studies have suggested that NFIX may have a putative role as a tumor suppressor, most studies have identified NFIX as an oncogene." (PMID 36901722, 2023). "This raises the possibility that NFIX is a critical factor for cell differentiation, which may be critical during tumor progression and metastasis." (PMID 36901722, 2023). "Further studies should be constructed to explore the effects of NFIX on tumor cell stemness and especially validate whether NFIX is involved in miR-375-mediated effects on GC cell stemness." (PMID 34090492, 2021). "Furthermore, similar patterns of the protein levels of NFIX and Ezrin in orthotopic tumor were observed compared with that of in vitro U87 cells." (PMID 32291386, 2020). "Overall, the results from our study demonstrated that LINC00511 could function as a tumor promoter by targeting miR-625-5p NFIX axis, suggesting LINC00511 could be considered as a target for GC treatment." (PMID 31889903, 2019). "The reported findings are compatible with a tumour suppressing role of NFIX, where reduced binding of this transcription factor to its recognition sequence may favour tumorigenic events." (PMID 18482459, 2008). "However, a significant upregulation of NFIX mRNA levels was observed in tumor tissues." (PMID 32219034, 2020). "Our study, for the first time, showed that NFIX is dramatically upregulated in GBM and plays a tumor-promoting role in GBM development." (PMID 32291386, 2020). "For the enhancer in chromosome 19, the target genes are TRMT1, TNPO2, NFIX, DNASE2, PRDX2, NANOS3, and LYL1, which was detected in 22 unique tumor samples." (PMID 29207666, 2017).
tumor (continued). "U87 cells transduced with lentiviral shNFIX (shNFIX-U87 cells) suppressed the tumor enlargement in the brain of nude mice as revealed by the in vivo bioluminescent imaging, suggesting that the malignant progression of GBM in the mice is attenuated by NFIX silencing." (PMID 32291386, 2020).
skeletal disease (2 papers, 2020 to 2022). "NFIX is associated with craniofacial skeletal disease phenotypes and related to speech capabilities, and it has already been highlighted for its role in the development of the AMH face and larynx." (PMID 35741749, 2022).
infection (1 paper, 2014). The state of being infected such as from the introduction of a foreign agent such as serum, vaccine, antigenic substance or organism. "Expression of the early astrocyte marker CD44 increased ∼2-fold with both HOPX and NFIX overexpression in fetal astrocytes (assayed three days post-infection)." (PMID 24848099, 2014). "We were unable to detect any significant differences in GFAP or HOPX staining between GFP and NFIX infections." (PMID 24848099, 2014).
skeletal dysplasia (1 paper, 2024). Any Mendelian diseases that affects growth and development of the skeleton. "Nuclear factor I/X (NFIX) mutations are associated with 2 skeletal dysplasias, Marshall-Smith (MSS) and Malan (MAL) syndromes." (PMID 38827116, 2024). "The resulting NFIX haploinsufficiency is associated with an overgrowth disorder called Malan (Sotos-like) syndrome (MAL; MIM ♯614 753), which is characterized by unusual facial phenotype, skeletal dysplasia, intellectual disability, and behavioral problems." (PMID 38827116, 2024).
NFIX also shares sentences with these, for which no sentence is quoted: overgrowth syndrome (5 papers); Cognitive impairment (2); esophageal cancer (2); genetic disorder (2); scoliosis (2); astrocytoma (1); benign prostate hyperplasia (1); bladder urothelial bladder carcinoma (1); Cirrhosis (1); colorectal adenocarcinoma (1); congenital hydrocephalus (1); COVID-19 (1); craniosynostosis (1); developmental disabilities (1); endocervical adenocarcinoma (1); endometrial carcinoma (1); gastric adenocarcinoma (1); heart failure (1); hydronephrosis (1); invasive ductal breast carcinoma (1); invasive lobular breast carcinoma (1); microdeletion syndrome (1); nephrocalcinosis (1); neurodevelopmental disorder (1); neurologic disorders (1); oral cavity squamous cell carcinoma (1); papillorenal syndromes (1); Pectus excavatum (1); Renal cyst (1); Respiratory distress (1).
A further 12 diseases each share a sentence with NFIX in 1 paper.